HCG21 (HLA complex group 21)
Synonyms: AB023048.2; NCRNA00150
Gene: Long non-coding RNA gene on chromosome 6 (30,945,979 to 30,954,862, reverse strand). Ensembl gene ENSG00000233529.
Diseases named in the same sentence as HCG21 in open-access papers:
HCG21 is named in the same sentence as 2 diseases in open-access papers, as found by Europe PMC text mining. Sharing a sentence is not in itself a finding about the gene and the disease. The quoted sentences say what the papers report.
Infertility (1 paper, 2020). "The variables included in the final predicting model were (hCG21, ratio of hCG21/hCG14, and main cause of infertility)." (PMID 32297865, 2020). "Here, through the multivariate multinomial logistic regression method, we have established a mathematical model to predict the probability of having an IUP, EP, or BCP in pregnant women subjected to ART using predictors of hCG21, ratio of hCG21/hCG14, and main cause of infertility." (PMID 32297865, 2020).
HCG21 also shares sentences with these, for which no sentence is quoted: coronary disease (1 paper).